ARF1 (ARF GTPase 1)
Description:
Small GTPase involved in protein trafficking between different compartments. Modulates vesicle budding and uncoating within the Golgi complex. In its GTP-bound form, triggers the recruitment of coatomer proteins to the Golgi membrane. The hydrolysis of ARF1-bound GTP, which is mediated by ARFGAPs proteins, is required for dissociation of coat proteins from Golgi membranes and vesicles. The GTP-bound form interacts with PICK1 to limit PICK1-mediated inhibition of Arp2/3 complex activity; the function is linked to AMPA receptor (AMPAR) trafficking, regulation of synaptic plasticity of excitatory synapses and spine shrinkage during long-term depression (LTD) (By similarity). Plays a key role in the regulation of intestinal stem cells and gut microbiota, and is essential for maintaining intestinal homeostasis (By similarity). Also plays a critical role in mast cell expansion but not in mast cell maturation by facilitating optimal mTORC1 activation (By similarity). (Microbial infection) Functions as an allosteric activator of the cholera toxin catalytic subunit, an ADP-ribosyltransferase.
Synonyms: PVNH8
Tractability: Small molecule: a structure with a bound ligand is known; it has a high-quality binding pocket. Antibody: its Gene Ontology location is reachable by antibodies, with high confidence; the Human Protein Atlas places it where antibodies can reach. PROTAC: ubiquitination databases record sites on it; a small molecule that binds it is known.
Gene: Protein-coding gene on chromosome 1 (228,081,841 to 228,099,212, forward strand). Ensembl gene ENSG00000143761.
Subcellular location: Golgi apparatus membrane; Synapse, synaptosome; Postsynaptic density
Subcellular location (Human Protein Atlas): Cytosol; Plasma membrane
Pathways (Reactome):
Vesicle-mediated transport: COPI-dependent Golgi-to-ER retrograde traffic; COPI-mediated anterograde transport; Golgi Associated Vesicle Biogenesis; Intra-Golgi traffic; Lysosome Vesicle Biogenesis; trans-Golgi Network Vesicle Budding
Immune System: Gene and protein expression by JAK-STAT signaling after Interleukin-12 stimulation; MHC class II antigen presentation
Metabolism: Synthesis of PIPs at the Golgi membrane; Synthesis of PIPs at the plasma membrane
Disease: Nef Mediated CD4 Down-regulation
Transport of small molecules: Glycosphingolipid transport
Gene Ontology:
Molecular function: G protein activity; GTPase activity; protein binding; protein domain specific binding; RNA binding; GTP binding; magnesium ion binding
Biological process: cellular response to virus; COPI-coated vesicle budding; glycolipid transport; intracellular copper ion homeostasis; protein localization to Golgi membrane; retrograde vesicle-mediated transport, Golgi to endoplasmic reticulum; dendritic spine organization; intracellular protein transport; long-term synaptic depression; regulation of Arp2/3 complex-mediated actin nucleation; regulation of receptor internalization; mitotic cleavage furrow ingression
Cellular component: cell leading edge; cytoplasmic side of trans-Golgi network membrane; extracellular exosome; focal adhesion; Golgi membrane; lysosomal membrane; protein-containing complex; cytosol; plasma membrane; postsynaptic density; endomembrane system; Golgi apparatus; sarcomere; synapse
Genetic constraint (gnomAD): Loss-of-function variants: 1 observed, 19.18 expected, observed/expected ratio (o/e) 0.0521, 90% interval 0.018 to 0.25. The upper end of that interval is the gene's LOEUF score, 0.25, which puts it in group 1 of 6, group 1 being the genes least tolerant of losing a copy. Missense variants: 73 observed, 254.56 expected, observed/expected ratio (o/e) 0.29, 90% interval 0.24 to 0.35. Synonymous variants: 112 observed, 100.43 expected, observed/expected ratio (o/e) 1.12, 90% interval 0.96 to 1.3.
Gene-disease validity (ClinGen):
ClinGen rates the evidence that ARF1 causes each of these diseases.
periventricular nodular heterotopia (autosomal dominant): Definitive. Periventricular nodular heterotopia (PNH) is a brain malformation, due to abnormal neuronal migration, in which a subset of neurons fails to migrate into the developing cerebral cortex and remains as nodules that line the ventricular surface.
Homologues: Orthologues: chimpanzee ARF1 (100% identical), dog ARF1 (100% identical), guinea pig ARF1 (100% identical), macaque ARF1 (100% identical), mouse Arf1 (100% identical), zebrafish arf2a (97% identical), Drosophila melanogaster Arf1 (96% identical), Caenorhabditis elegans arf-1 (93% identical). Paralogues in human: ARF3 (96% identical), ARF5 (80% identical), ARF4 (80% identical), ARF6 (68% identical), TRIM23 (61% identical), ARL1 (56% identical), ARL5B (50% identical), ARL4C (49% identical), ARL5A (49% identical), ARL2 (46% identical), ARL3 (46% identical), ARL4A (46% identical), and 18 more.
Diseases named in the same sentence as ARF1 in open-access papers:
ARF1 is named in the same sentence as 90 diseases in open-access papers, as found by Europe PMC text mining. Sharing a sentence is not in itself a finding about the gene and the disease. The quoted sentences say what the papers report.
breast carcinoma (35 papers, 2010 to 2026). "In this context, it is worth noting that ACBD3, Arf1, PI4Kβ and Rab4A all have been implicated in breast cancer progression and prognosis and found to be coordinately regulated in the same region of chromosome 1q." (PMID 37048152, 2023). "Amplification of Arf1 has been found in 2.3% of cancer patients belonging to different subtypes and associated with poor prognosis of breast cancer patients." (PMID 35465326, 2022). "Amplification of ADP-ribosylation factor 1 (ARF1) is associated with poor outcomes of patients with breast cancer." (PMID 29376139, 2017). "Orthotopic implantation in mice indicates that loss of ARF1 expression in breast cancer cells reduces risk of metastatic spread." (PMID 27517156, 2016). "Most interestingly, higher levels of ARF1 were associated with higher cancer stages, supporting its critical role in breast cancer progression." (PMID 27517156, 2016). "Using the orthotopic xenograft model in NSG mice, we demonstrate that loss of ARF1 expression in breast cancer cells inhibits pulmonary metastasis." (PMID 27517156, 2016). "Altogether, our results indicate that overexpression of ARF1 is closely associated with the most lethal and advanced forms of breast cancers." (PMID 26908458, 2016). "For the first time, we demonstrate that elevated level of ARF1 is associated with a higher incidence of metastases and that its expression is elevated in high-grade cancers and triple-negative basal-like breast cancers." (PMID 26908458, 2016). "Although the stroma contributes to tumor progression, depletion of ARF1, in invasive breast cancer cells, is associated with a significant decrease of malignant potential." (PMID 26908458, 2016). "In addition, in invasive breast cancer cells, ARF1 constitutively binds Rac1, a Rho GTPase associated with lamellipodia formation during cell migration." (PMID 35805075, 2022). "We report for the first time that ADP-ribosylation factor 1 (ARF1) is the most amplified gene in ARF gene family in breast cancer, and high-level amplification of ARF1 is associated with increased mRNA expression and poor outcomes of patients with breast cancer." (PMID 27517156, 2016). "Interestingly, Arf1 has also been implicated in recruitment of p85 subunits of PI3K to EGFR in breast cancer cells, providing an additional possible mechanism by which VAPB could regulate AKT activities." (PMID 23049696, 2012). "Previous work has implicated CADs in the activation of ARF1 and regulation of tumor cell survival, and independent studies have established ARF1 as a driver of growth, migration and metastasis in breast cancer." (PMID 41465279, 2025). "A study on the regulation of the Rho/MLC pathway by ADP-ribosylation factor 1 (ARF1) for controlling breast cancer cell invasion demonstrated that ARF1 also functions like ARF6 and plays a crucial role in the contractile machinery of the cytoskeleton." (PMID 39773634, 2025). "In fact, ARF1 is the most frequently amplified ARF family member in breast cancer, and its depletion suppresses metastatic dissemination in mice and zebrafish models." (PMID 41465279, 2025). "Conversely, ARF1 knockdown in breast cancer models impairs primary tumor growth and markedly reduces lung metastases, highlighting its role in cellular trafficking and cancer progression." (PMID 41465279, 2025). "High ARF1 expression is observed in aggressive breast cancer subtypes, and ARF1 promotes metastatic behavior." (PMID 41465279, 2025). "That depletion of Class I ARFs induced invasive activity was somewhat unexpected, as numerous studies, particularly in breast cancer cells, report a pro-invasive and pro-tumorigenic function of ARF1." (PMID 36880595, 2023). "ARF1 regulates the proliferation of breast cancer cells by modulating pRb hyperphosphorylation and its association with E2F1." (PMID 35805075, 2022).
breast carcinoma (continued). "Another mechanism by which ARF1 regulates the migration of highly invasive breast cancer cells consists of controlling an EGF-dependent assembly of focal adhesions." (PMID 35805075, 2022). "Arf1 overexpression promotes growth and metastasis in breast cancer, myeloma cells and ovarian tumors." (PMID 35465326, 2022). "Schlienger S and collaborators unravel an additional mechanism by which ARF1 supports the invasion of breast cancer cells." (PMID 35805075, 2022). "In breast cancer, Arf1 controls cell proliferation by regulating the retinoblastoma protein and acts as a molecular switch to activate EGF-mediated responses." (PMID 31991585, 2020). "Amplification is the predominant type of alteration for Arf1 in breast cancer cells, and its frequency was much higher than other Arf family members." (PMID 30777099, 2019). "We previously reported that a small molecule LM11 can effectively impair Arf1 activation in breast cancer cells and suppress their metastatic capability in zebrafish." (PMID 28830537, 2017). "A zebrafish xenograft model demonstrated that specific inhibition of Arf1 by small molecule LM11 impairs metastatic capability of breast cancer cells." (PMID 29376139, 2017). "Amplification was the predominant type of alteration for ARF1 gene and its frequency was much higher (14% of cases) than other family members in breast cancer." (PMID 27517156, 2016). "Knockdown of ARF1 leads to significant suppression of migration and invasion in breast cancer cells." (PMID 27517156, 2016). "Our data indicate remarkably increased levels of ARF1 in primary breast cancer tissues compared with normal breast epithelium, and strong membrane staining of ARF1 in advanced breast cancer." (PMID 27517156, 2016). "Considering that NSG mice allow primary and metastatic tumors to develop coincidently, we established orthotopic breast cancer models in NSG mice to illustrate the contribution of ARF1 alteration to cancer progression." (PMID 27517156, 2016). "Variations in the levels of ARF1 expression according to molecular subtypes of breast cancer were assessed." (PMID 26908458, 2016). "To better understand the role of ARF1 in breast cancer, we used shRNA constructs to inhibit ARF1 expression in high-invasive breast cancer MDA-MB-231 cells." (PMID 27517156, 2016). "Here we provide evidence for such a role, and demonstrate that ARF1 is a very compelling target to limit breast cancer metastasis." (PMID 27517156, 2016). "We found a positive correlation between elevated levels of ARF1 and breast cancer of higher histological grades." (PMID 26908458, 2016). "The data present here, for the first time, show potential therapeutic opportunities for breast cancer resulting from ARF1 inactivation in the context of LM11 treatment." (PMID 27517156, 2016). "Here we show that ARF1 is often abnormally overexpressed in breast cancer cells, and such overexpression is crucial to promote invasion and metastasis to be significantly associated with the poor outcomes of patients." (PMID 27517156, 2016). "Our findings reveal the importance of ARF1 in the most lethal forms of breast cancer and identify this GTPase as a potential new target for the design of next generation breast cancer treatments." (PMID 26908458, 2016). "In breast cancer, ARF1 has been reported to be involved in promoting cell proliferation and migration via multiple well-known signaling cascades." (PMID 27517156, 2016). "Although all subtypes were found to be positive for ARF1, samples collected from patients with luminal A and luminal B breast cancer had the lowest level of this ARF isoform." (PMID 26908458, 2016). "Taken together, these data demonstrate that inhibition of ARF1 expression, in highly invasive breast cancer cells, decreased both primary breast tumor formation and metastatic breast tumors within the lung." (PMID 26908458, 2016).
breast carcinoma (continued). "The zebrafish-metastasis model confirms that the ARF1 gene depletion suppresses breast cancer cells to metastatic disseminate throughout fish body, indicating that ARF1 is a very compelling target to limit metastasis." (PMID 27517156, 2016). "We next determined levels of ARF1 expression and activation status in well-established human breast cancer cell lines." (PMID 27517156, 2016). "To support this, we show here that in tissue samples from breast cancer patients, overall expression level of ARF1 is correlated with the most aggressive subtypes of tumor and high-grade breast cancer." (PMID 26908458, 2016). "In cancer biology, ARF1 has been shown to regulate proliferation and migration of breast cancer cells which is mediated through the phosphoinositide 3-kinase (PI3K) pathway, the retinoblastoma protein and Rac1." (PMID 27213581, 2016). "In this report, we describe the molecular mechanism by which ARF1 confers an invasive phenotype to breast cancer cells and show that in vivo, this key molecular switch greatly contributes to tumorigenesis." (PMID 26908458, 2016). "Based on these facts, we demonstrate that ARF1 serves as a previously unidentified drug target and inactivating it can suppress metastatic breast cancer." (PMID 27517156, 2016). "Inhibition of endogenous Arf1 expression resulted in the suppression of breast cancer cell migration and proliferation through activation of the phosphatidylinositol 3-kinase pathway." (PMID 25754106, 2015). "Consistent with our results, depletion of ARF1 has been reported to inhibit proliferation and migration of breast cancer cells, indicating that ARF1 is involved in cell proliferation and migration." (PMID 26690137, 2015). "The ezrin gene set also contains ARF1, which is reported to modulate migration and proliferation in breast cancer cell lines via the regulation of the PI3K pathway." (PMID 20731868, 2010). "Moreover, Drp1 activity and mitochondrial fission have been repeatedly implicated in breast cancer biology, including TNBC, providing a mechanistic bridge between ARF1 signaling and mitochondrial dynamics." (PMID 41465279, 2025). "This led us to further investigate the expression and clinical relevance of ARF1 in breast cancer." (PMID 41465279, 2025). "The dysregulation of ARF1 expression and activity is involved in breast cancer." (PMID 36276611, 2022). "T-96 could inhibit breast cancer proliferation via inhibiting hyperphosphorylation of pRB and its downstream pathway by targeting ARF1." (PMID 36276611, 2022). "Several papers have reported that ARF1 could promote tumor development and metastasis in other cancer types, including breast cancer, cervical cancer, prostate cancer, head and neck squamous cell carcinoma." (PMID 34805171, 2021). "It has been reported that ARF1 may activate the ERK pathway in breast cancer 19 and induce cell adhesion-mediated drug resistance by activating AKT and ERK signaling in multiple myeloma cells." (PMID 33408784, 2021). "Other researchers also concluded that altered expression of some genes (RRM2, SPP1, MMP9, Arf1) could be involved in increased cell proliferation of adipose tissue in breast cancer risks." (PMID 34657612, 2021). "Moreover, knockdown of Arf1 expression markedly inhibited cell proliferation in invasive breast cancer cells." (PMID 31991585, 2020). "Furthermore, ARF1 sensitizes MDA-MB-231 breast cancer cells to the anti-tumor drugs actinomycin D and vinblastine through ERK and Akt signaling." (PMID 32426352, 2020). "Moreover, ARF1 regulates breast cancer cell adhesion and proliferation, being essential for EGF-mediated phosphorylation of Focal Adhesion Kinase (FAK) and Src." (PMID 32426352, 2020). "Arf1 has been reported to be critical for breast cancer cell invasion and metastasis." (PMID 30777099, 2019).